CXCL1 (C-X-C motif chemokine ligand 1)
Diseases named in the same sentence as CXCL1 in open-access papers (continued):
Sharing a sentence is not in itself a finding about the gene and the disease.
tumor (continued). "CXCL1 expression level in tumor cells is positively correlated with N stage, T stage, and distant metastasis, but not with perineural invasion." (PMID 37408240, 2023). "As shown, compared to paternal Setd2KO cells, Cxadr overexpression retarded tumor growth and reduced serum CXCL1 and GM‐CSF levels in the corresponding tumor‐bearing mice." (PMID 36453584, 2023). "Significant hypomethylation of the CXCL1 promoter region in primary tumor samples compared to normal, which is consistent with overexpression, suggests DNA methylation-based epigenetic regulation in these samples." (PMID 36614235, 2023). "CXCL1 and CXCL2 are also associated with tumor progression, including tumor growth, angiogenesis, and metastasis via enhancing cell proliferation and the invasion of cancer cells." (PMID 36661524, 2023). "Cxcl1 has an oncogenic role in HCC progression, as it is associated with tumor progression and recurrence in HCC patients." (PMID 36980965, 2023). "IL-17-induced inflammatory mediators such as G-CSF, IL-6, and CXCL1 stimulate the expansion and recruitment of dysfunctional myeloid cells to establish a proangiogenic and immune-suppressive tumor environment that enhances tumor growth and metastasis." (PMID 36993955, 2023). "We found that many myeloid cell markers were highly expressed in hybrid tumor cells, including Ly6e, Ly6c2, Ccl2, Nos2, Cxcl1, and Cxcl2." (PMID 37138326, 2023). "More importantly, CXCL1 knockdown in the primary tumor significantly attenuated the recruitment of exogenous mCherry-MDSCs into the lung, validating the crucial role of CXCL1 in mobilizing MDSCs." (PMID 37210553, 2023). "In summary, tumor cell-derived chemokines and cytokines, such as CXCL1/CXCL8 and SRF, recruit MDSCs, TAMs, Treg and Tex, and interact with target genes, like MIF and IFNG." (PMID 37940972, 2023). "In summary, these results suggest that TRIM28 in tumor cells induces the activation of the NF-κB pathway, which contributes to the expression of CXCL1." (PMID 37865804, 2023). "Based on sample types, the median CXCL1 promoter methylation beta value was 0.078 in the primary tumor and 0.223 in the normal stomach." (PMID 36614235, 2023). "CXCL1 induces the recruitment of neutrophils into the HCC tumor niche; these cells secrete CCL2 and C-C motif ligand 17 (CCL17, thymus and activation-regulated chemokine (TARC)), which induce the recruitment of monocytes and Treg, respectively." (PMID 37408240, 2023). "Certain specific pathogens such as F. nucleatum and P. anaerobius can induce tumor-derived chemokine CXCL1 to recruit the MDSCs, thereby suppressing anti-tumor immunity." (PMID 38023192, 2023). "Overexpression of c-Met in tumor cells enhances the secretion of a group of cytokines, including CXCL1/2, G-CSF, and GM-CSF, which play critical roles in neutrophil attraction, granulopoiesis, and homeostasis." (PMID 37174093, 2023). "Negative regulation of the immune response mediated by CXCL1 involving tumour cells and macrophages in the microenvironment of HCC has been investigated in vivo and in vitro." (PMID 37037815, 2023). "Data from both in vivo and in vitro models showed that the CXCR2/CXCL1 axis as well as the CXCR2/CXCL5 axis regulate neutrophil infiltration into tumor tissues, inducing epithelial–mesenchymal transition and thus aggravating malignant behavior of HCC cells." (PMID 36982370, 2023). "The level of CXCL1 was higher in tumours that were injected with HCC cells stimulated with CXCL1 recombinant protein than in those injected with control cells." (PMID 37037815, 2023). "In contrast to the effects of recombinant CXCL1 treatment, CXCL1-downregulation slowed tumour growth and decreased the number of cells that migrated through the membrane with or without Matrigel coating." (PMID 37037815, 2023). "Selectively targeting HDAC6 also blocks CXCL1 signalling to advance anti-cancer therapy by repressing tumour invasion and migration." (PMID 36810912, 2023).
tumor (continued). "It has been shown that miR-200a, a microRNA that directly downregulates CXCL1 expression, is downregulated in this tumor, and thus increases CXCL1 expression in HCC tumors." (PMID 37408240, 2023). "CXCL1 enhanced tumorigenesis in the hepatic inflammatory microenvironment directly by acting on tumour cells and indirectly through promoting the recruitment of macrophages." (PMID 37037815, 2023). "Next, we examined the expression of three ER stress-related cytokines identified from ContactTracing, Ccl2, Cxcl1 and Il11, in 4T1 cells and validated their dependence on tumour-intrinsic STING activation." (PMID 37612508, 2023). "Oncostatin M, which is secreted by tumor-associated neutrophils (TAN) and tumor-associated macrophages (TAM), is also responsible for the increase in CXCL1 expression in CAF." (PMID 37108425, 2023). "IL-17A promotes the expression of IL-6, G-CSF, MFG-E8, and CXCL1 in NSCLC tumor tissues to increase tumor-associated neutrophils (TANs) infiltration and reduce the number of tumor-infiltrating lymphocytes (TILs), leading to drug resistance to PD-1 inhibitors." (PMID 37978543, 2023). "This showed that the combination strategy was effective in reducing peripheral macrophage recruitment into the TME and suppressing the pro-tumour phenotype induced by reducing CXCL1 expression." (PMID 37037815, 2023). "Cxcl1 transcription in CAFs—another key iCAF marker—was similarly induced nearly 22-fold following co-culture with tumor-infiltrating neutrophils, and significantly abrogated with either IL-1β or IL-1R1 inhibition (all p<0.0001)." (PMID 36107485, 2022). "In the tumor microenvironment, macrophages and other stromal cells promote CXCL1 expression in cancer cells to promote cancer survival at metastatic sites." (PMID 36552865, 2022). "The introduction of recombinant KLK6 protein in KLK6−/− mice rescued the production of TNF-α and CXCL1, tumor growth, and metastasis." (PMID 36552865, 2022). "Previous research has shown that CXCL1 produced by tumor cells enhances MDSC recruitment and infiltration to the tumor site, facilitating CRC metastasis." (PMID 35183163, 2022). "In the current study, inhibition of CXCL1 using a neutralizing antibody suppressed tumor growth and lung metastasis in vivo." (PMID 36552865, 2022). "We also explored the potential exogenous autocrine and paracrine mechanisms involved in CXCL1-mediated UCC tumor biology, possibly via mitogen activated protein kinases (MAPK)/extracellular signal-regulated kinase (ERK)-dependent signal pathway." (PMID 35764974, 2022). "All the pro-tumor properties of CXCL1 are confirmed by clinical tumor studies, which showed that CXCL1 expression increased with cancer progression." (PMID 35054978, 2022). "For example, anti-vascular endothelial growth factor (VEGF) agents (e.g., apatinib and bevacizumab) have shown positive effects on tumor vascular normalization and rescued infiltration of T cells into the tumor bed with an increase in chemokines (e.g., CXCL1)." (PMID 36015215, 2022). "Clones of macrophages and fibroblasts isolated from human bladder cancer tumors synthesize CXCL1 in response to which neutrophils and other cell populations migrate to the tumor." (PMID 36286054, 2022). "For example, several studies have found elevated levels of CXCL1 in plasma, serum, ascitic fluid, and tumor tissue of patients with ovarian cancer." (PMID 36434686, 2022). "Expression of the iCAF markers Il6, Cxcl1, and Lif was markedly elevated in hypoxic PSCs cocultured with tumor organoids relative to their normoxic counterparts." (PMID 36109493, 2022). "Generally, CCL17 weakly and positively correlated with early factors of tumour grow (CXCL10), but then weakly and negatively correlated with late factors of tumour growth (myeloid cell populations); CXCL1 and CCL2 acted like CCL17 in this respect." (PMID 35226704, 2022).
tumor (continued). "CXCL1 expressed by stromal breast CAFs is correlated with tumor grade, disease recurrence, and decreased patient survival." (PMID 35454913, 2022). "CXCL1 has already been identified as one secreted factor from CAFs that can promote tumor progression." (PMID 35803738, 2022). "CXCR2 inhibition also suppressed the increase in tumor cell transendothelial migration in response to CXCL1." (PMID 36077870, 2022). "CXCR2 is not normally expressed on T cells but is specific for a variety of ligands overexpressed on a range of tumours, including CXCL1, CXCL2, CXCL5, and CXCL8." (PMID 35205725, 2022). "Meanwhile, the CXCL1/CXCR2 signaling pathway was also thought to play important roles in regulating tumor growth and promoting tumor metastasis." (PMID 36117156, 2022). "In particular, CXC ligand 1 (CXCL1), CXCL10 and CXCL13 have recently been associated with tumor survival, metastasis and angiogenesis." (PMID 36077611, 2022). "We have observed that CXCL1 gene was closely linked with preoperative CEA level (P=0.007) and gross tumor typing (P=0.039)." (PMID 35958781, 2022). "In line with this, our results showed that the PAR1 inhibitor suppressed TNF-α and CXCL1 production and rKLK6-promoted tumor growth and metastasis in the xenograft model, suggesting that PAR1 plays a critical role in KLK6-mediated malignant progression." (PMID 36552865, 2022). "These phenotypes are contributing to the severity of BMA-induced tumor burden, by driving osteoclastogenesis and thereby osteolytic lesion formation via IL-6 or indirectly via CXCL1 and osteopontin (OPN)." (PMID 35800430, 2022). "And IL-33 can stimulate the production of cytokines (IL-4, IL-6) and chemokines (CCL2, CCL3, CCL7, CXCL1), which are also involved in the construction of the tumor microenvironment." (PMID 36110250, 2022). "Produced by lymphatic endothelial cells (LECs), CXCL1 enables tumor cell migration into the lymphatic vessels during lymphangiogenesis, leading to lymph node metastasis." (PMID 35054978, 2022). "In concert with tumor-derived chemokines (e.g., CXCL1, CCL2, and INFγ), CXC chemokines produced by tissue-resident immune cells promote the accumulation of neutrophils within the TME." (PMID 35504900, 2022). "CXCL1 is known to be involved in cancer development and malignant progression including tumor growth, metastasis, and chemoresistance." (PMID 36552865, 2022). "Previous researches focused on the relationship of hypoxia and CXCL1 in tumor, and showed the effect of hypoxia on the expression of CXCL1 depended on the type of cancer." (PMID 36244759, 2022). "The IL-1β expressed by tumor cells can significantly increase CXCL1 production in CAFs via paracrine signaling." (PMID 36275775, 2022). "After being arrested, PMNs were further sequestered by self-secreted IL-8 and tumor-derived CXCL-1 to form tumor cell-PMN clusters." (PMID 35158914, 2022). "GNA13, belonging to a subfamily of G protein-coupled receptors of the Gα subunit, promotes tumor growth and angiogenesis by upregulating CXCL1, CXCL2, and CXCL4 via the IKKβ/NF-κB signaling pathway in CRC cells." (PMID 35935996, 2022). "CXCL1 and CXCL5 activation; Loss of blood flow to the interior of the tumor induced by neutrophil accumulation." (PMID 35640930, 2022). "Soluble mediators from cancer cells and stromal cells such as Cxcl1, Ccl2, Vegf family, Tgf‐β and GM‐CSF are reported to participate in tumour development." (PMID 35170261, 2022). "Although an oversimplification, for charting purposes, the cytokines were split into three groups by their generalized tumor-destroying (IFN-γ, IL-2, and IL-5), tumor-promoting (IL-10 and IL-4), or SIRS-associated (IL-1β, IL-6, CXCL-1, and TNF-α) properties." (PMID 35465347, 2022).
tumor (continued). "CXCL1 is produced in the tumor by cancer cells, and also by CAFs, MDSCs, mesenchymal stem cells (MSCs) and tumor-associated macrophages (TAMs)." (PMID 35054978, 2022). "NMU overexpression in HT29 cells induced or increased the secretion of tumour supporting cytokines (CXCL1/GROa, CXCL10/IP-10 and ICAM-1/CD54, CCL-5/RANTES, IL-8 and IL-1ra)." (PMID 36482448, 2022). "Based on a gene expression microarray and a protein array analyses, IL-1, IL-6, IL-8, and CXCL1 were chosen as candidates responsible for tumor-induced osteoclastogenesis." (PMID 36614130, 2022). "Next, we analyzed MDSC chemotaxis-related genes, including Cxcl1, Cxcl2, Cxcl5, and Cxcl12 in tumor tissues." (PMID 34976216, 2022). "For example, neutrophil-derived IL-8 and tumor-derived CXCL1 are involved in the interaction of tumor and the LPS-stimulated neutrophils, resulting in tumor cell extravasation and distant metastasis." (PMID 36612163, 2022). "In the mouse model, treatment with P300 inhibitor, C646, led to significant inhibition of tumor growth after overexpression of CXCL1." (PMID 36434686, 2022). "Recruitment of circulating neutrophils in tumor tissues is mainly regulated by CXCL1, CXCL2, CXCL8 and CXCL5 chemokines, the complement component anaphylatoxin C5a and tumor-derived oxysterols." (PMID 35158779, 2022). "Elevated levels of G-CSF, IL-6 and CXCL13, and B cell counts were associated with 4T1 growth, whereas CCL17, CXCL10, total myeloid cells, CCL2, IL-10, CXCL1, and Ly6Cintermediate monocytes were associated with CT26 tumour development." (PMID 35226704, 2022). "Tumor-associated macrophages (TAMs) have been reported to be associated consisting of highly expressed CCL2, CCL3, CCL5, CCL18, CXCL1, and CXCL12 in the TME." (PMID 35935996, 2022). "After anti-HER2 treatment, for the tumor with HER2 amplification, the release of cytokines such as CCL2, CCL21, VEGF, and CXCL1 was downregulated, and the immunosuppressive factors of the tumor microenvironment were improved." (PMID 36211361, 2022). "In this context, it has also been demonstrated that tumour-derived CXCL1 and CXCL5 influence in DC maturation, as reported in human CRC." (PMID 35406451, 2022). "Our findings are in line with studies demonstrating a role of CXCL-1, IL-6 and IL-8 in tumor cell migration and metastasis in other tumor entities." (PMID 35628911, 2022). "CXCL1 inhibition by neutralizing antibodies also attenuated rKLK6-promoted tumor growth and lung metastasis." (PMID 36552865, 2022). "We confirmed that Cxcl1 and Ccl2 were the two mediators present in tumour conditioned medium of GK1 cells." (PMID 35170261, 2022). "After carcinogen-induced expression, CXCL1 can lead to chronic inflammation by recruiting neutrophils, resulting in tumor formation." (PMID 36434686, 2022). "Our analysis was devoted to both receptors (CXCR1/2) and ELR+CXCL cytokines (CXCL1, 2, 3, 5, 6, 7, 8) selected from six independent datasets (M1–M6) and compared with datasets from a normal brain (NB) and a tumour brain (TB)." (PMID 36497191, 2022). "CXCR2, the CXC receptor expressed by neutrophils, can bind with its ligand chemokine family (CXCL1, CXCL2, CXCL3, CXCL5, CXCL7, and CXCL8) to recruit neutrophils to the TME and participate in the mobilization of tumour-associated neutrophils." (PMID 36743929, 2022). "In melanoma tumor, the level of CXCL1, CXCL2, and CXCL3 is significantly elevated, accompanied by proangiogenic activity." (PMID 36612163, 2022). "Activated CXCL1 is significantly related to the growth, proliferation, tumor angiogenesis, and metastasis of CRC cells." (PMID 35845924, 2022). "CXCL1 has a role in angiogenesis and thus has been shown to act in the process of tumor progression (n = 10)." (PMID 35628865, 2022). "A direct talk has also been found between CXCL1 and tumor cells where CXCL1 induces the production of VEGF by tumor cells." (PMID 35626056, 2022).
tumor (continued). "CXCR2 acts as receptor for the chemokines CXCL1–3, 5–8, and its stimulation activates several signaling pathways beneath NFκB, which are involved in tumor cell survival and proliferation." (PMID 35530351, 2022). "We have previously shown that gemcitabine enhanced necroptosis in PDAC, which, in turn, promoted macrophage-induced adaptive immune suppression and tumor progression through CXCL1 and Mincle signaling." (PMID 36509285, 2022). "CAF‐derived chemokines like Cxcl1, Cxcl12, and Cxcl2 also recruit a heterogeneous population of largely immunosuppressive or tumour‐promoting myeloid‐derived cells, including monocytes, macrophages, neutrophils, and MDSCs, at least in murine studies." (PMID 35533046, 2022). "In CRC, macrophages stimulate the primary tumor to produce CXCL1, a member of CXC chemokines, binding to CXCR2 together with CXCL2, CXCL5, and CXCL8." (PMID 35879739, 2022). "The RNA-Seq analysis revealed a striking reduction in the expression of multiple chemokines, including CXCL1, which are known to stimulate cancer cell invasion and immune cell recruitment to the tumor." (PMID 35998057, 2022). "In response to OV therapy, neutrophils can accumulate in the tumour, destroying the tumour vasculature and inducing apoptosis through secretion of reactive oxygen species, cytokines and proteases, including CXCL1 and CXCL5." (PMID 34888493, 2021). "The growth factor activity of CXCL1 in BCSCs led us to assess the extent of its expression in tumor tissues from BC patients in order to determine its clinic-pathological impact." (PMID 34195201, 2021). "It was demonstrated that CXCL1, secreted from tumor cells, induced migration of vascular endothelial cells and angiogenesis in vitro." (PMID 33826043, 2021). "Lung epithelial cells, when exposed to tumor-derived exosomal RNAs, are also able to recruit neutrophils by secreting CXCL1, CXCL2, CXCL5, and CXCL1214." (PMID 34707103, 2021). "During hepatocyte senescence, Cox2 is critical to tumor suppression, Cxcl1 expression, the immune microenvironment, and immune-mediated senescence surveillance, partially through PGE2." (PMID 33730589, 2021). "Chemotactic cytokines involved in the immune response include CXCL1, CXCL3, and CXCL3, which are closely associated with tumor transformation and angiogenesis." (PMID 34442627, 2021). "The N2 phenotype shows a proneoplastic action through the enhancement of MMP-9 expression and release of CXCL-1 and -6, which recruit new proinflammatory cells to the tumor microenvironment." (PMID 33146401, 2021). "Paired t-test analysis showed that the immunohistochemical score of CXCL1 in COAD carcinoma was considerably higher than that in paracancerous non-tumor colon tissues." (PMID 34405013, 2021). "The expression of CXCL1 gene in COAD tumor tissues was significantly higher than that in normal colon tissues." (PMID 34405013, 2021). "The levels of the cytokine CXCL1/KC were markedly increased inside spheroids, and a concentration gradient was established between the inside and outside (supernatant medium) of the tumor spheres during growth monitoring." (PMID 34715854, 2021). "As previously reported, tumor-associated macrophages in primary CRC tumors recruit MDSCs into the liver and generate pre-metastatic sites through the CXCL1/CXCR2 pathway." (PMID 33833986, 2021). "CD11b (+) Gr1(+) myeloid cells are pushed by CXCL-1/2 into the tumour, leading to the production of chemokines like S100A8/9 which augment chemoresistance, metastasis, and cancer cell survival." (PMID 34336101, 2021). "Specifically, tumor-derived PGE2 directly induces the production of cancer-promoting inflammatory mediators, such as IL-6, CXCL1, and G-CSF, by myeloid cells, while preventing the activation of anti-tumor type I immune responses." (PMID 34063828, 2021). "Anti-CXCL8 antibody, CXCL8 small interfering RNA, and anti-CXCL1 antibody have also been tested and such therapies have shown a reduction in tumor cell migration and angiogenesis." (PMID 33467722, 2021).